RNU6-41P (RNA, U6 small nuclear 41, pseudogene)
Synonyms: RNU6-41
Gene: Small nuclear RNA gene on chromosome 1 (182,982,212 to 182,982,318, reverse strand). Ensembl gene ENSG00000207472.
Homologues: Orthologues: mouse Gm26138 (99% identical), pig U6 (92% identical). Paralogues in human: RNU6-12P (98% identical), RNU6-13P (98% identical), RNU6-25P (98% identical), RNU6-32P (98% identical), RNU6-44P (98% identical), RNU6-1 (97% identical), RNU6-15P (97% identical), RNU6-17P (97% identical), RNU6-18P (97% identical), RNU6-2 (97% identical), RNU6-3P (97% identical), RNU6-4P (97% identical), and 1287 more.